CDO1 (cysteine dioxygenase type 1)
Diseases named in the same sentence as CDO1 in open-access papers (continued):
Sharing a sentence is not in itself a finding about the gene and the disease.
gastric cancer (continued). "Almost cancer cell lines including gastric cancer did not recognize CDO1 gene expression, and it is therefore difficult to conduct an experiment to suppress expression of CDO1 gene by RNA interference using siRNA." (PMID 30934021, 2019). "Nevertheless, we have not found any reports on the clinical significance of CDO1 gene methylation in primary gastric cancer." (PMID 30934021, 2019). "Methylation of the promoter region of the CDO1 has been reported in a number of cancers including breast cancer, esophageal cancer, gastric cancer, and colon cancer, however there has no report with regard to SBC." (PMID 30677088, 2019). "In order to know the biological role of CDO1 gene during natural clinical course, we had better not include gastric cancer with adjuvant chemotherapy." (PMID 30934021, 2019). "CDO1 gene actually suppressed anchorage independent growth in Kato III cells, suggesting that it plays a functionally critical role in distant metastasis of gastric cancer." (PMID 30934021, 2019). "To examine the expression of CDO1 in primary cancer, we performed qRT-PCR analysis with cDNAs derived from patients with colon, breast, esophagus, bladder and stomach cancer (T, n = 1 for each tumor) and patients without cancer (NN, n = 1 for each normal)." (PMID 23028699, 2012). "Expression of CDO1 gene was never observed in 6 gastric cancer cell lines, as compared with positive expression control of HepG2 cells at mRNA level, where DNA hypermethylation was confirmed in all the 6 cell lines and DNA hypomethylation was seen in HepG2 cells." (PMID 30934021, 2019). "CDO1 gene hypermethylation could predict poorer prognosis of pStage II / III gastric cancer without adjuvant chemotherapy than CDO1 gene hypomethylation (5-year OS 53.8% / 76.3% in the H / L group, respectively) (p = 0.0067)." (PMID 30934021, 2019). "The cut-off TaqMeth values of CDO1, HOPX, and Reprimo obtained from comparison between RGC tumor tissues and the RN were very similar with those primary ones, indicating that pin-point dense methylation event may result in cancer formation of both RGC and primary gastric cancer." (PMID 31069006, 2019). "In the present study, epigenetic field cancerization was assessed in non-cancerous sites for cysteine dioxygenase 1 (CDO1), homeodomain-only protein X (HOPX), Reprimo, and E-cadherin, because they were cancer-specific and frequent aberrations in gastric cancer." (PMID 31069006, 2019).
breast carcinoma (16 papers, 2010 to 2024). "Cancer types in which Cdo1 mutation and structural variation are relatively common are melanoma, breast cancer, and pancreatic cancer." (PMID 38672271, 2024). "Additionally, we and others investigated strong association of CDO1 gene promoter DNA methylation with poor prognosis in primary breast cancer, renal clear-cell cancer, esophageal squamous cell carcinoma and Barrett esophagus adenocarcinoma." (PMID 29161283, 2017). "In general, the gene expression analysis showed that Cdo1-overexpressing breast cancer cells had lower expression of metastatic and aggressiveness-related genes." (PMID 38672271, 2024). "Cysteine dioxygenase 1 (CDO1) is frequently methylated, and its expression is decreased in many human cancers including breast cancer (BC)." (PMID 37740473, 2023). "In breast cancer cells, CDO1 restoration leads to increased ROS levels, resulting in reduced viability and growth, as well as anthracycline sensitization." (PMID 36059650, 2022). "This demonstrates the importance of CDO1 inactivation in breast cancer and its potential as a biomarker and treatment target for overcoming anthracycline resistance." (PMID 36059650, 2022). "Two enzymes of this pathway, cystathionine beta synthase (CBS) and cysteine dioxygenase type 1 (CDO1), are often silenced by epigenetic inactivation in gastric and breast cancer, respectively." (PMID 28931650, 2017). "For instance, transcription factor SOX17 (SOX17), slit guidance ligand 3 (SLIT3), and cysteine dioxygenase type 1 (CDO1) that are frequently suppressed by hypermethylation in breast cancer, turned hypomethylated after resveratrol treatment." (PMID 27355345, 2016). "Specifically, Dietrich and colleagues identified CDO1 promoter methylation in breast cancer and demonstrated its capacity to serve as a predictive factor for distant metastases." (PMID 24351290, 2014). "CDO1 methylation was shown to be a strong predictor for distant metastasis in retrospective cohorts of LNP/ER+ breast cancer patients, who had received adjuvant anthracycline-based chemotherapy." (PMID 20515469, 2010). "In breast cancer patients, those with Cdo1 promoter hypermethylation showed a worse prognosis." (PMID 38672271, 2024). "Therefore, studies have shown that these two drugs have a better therapeutic effect in CDO1 overexpressing breast cancer cells." (PMID 35359956, 2022). "In addition to breast cancer, promoter DNA hypermethylation of CDO1 gene has been reported to be highly specific to cancer cells, and exhibited prognostic relevance in specific cancers such as esophageal, lung, colorectal, gallbladder, and kidney cancer." (PMID 30934021, 2019). "However, cysteine dioxygenase type 1 (CDO1) overexpression can reduce GSH expression and ROS accumulation in breast cancer cells." (PMID 35359956, 2022). "In this study, we assessed the clinicopathological significance of CDO1 methylation in primary breast cancer (BC) with no prior chemotherapy." (PMID 26785325, 2016). "Nonetheless, as of today, no aberrant DNA methylation of the CDO1 gene has been described in the context of breast cancer." (PMID 20515469, 2010).
colorectal cancer (8 papers, 2014 to 2023). A primary or metastatic malignant neoplasm that affects the colon or rectum. "As a positive control, DLD1 (colorectal cancer cell line) and HepG2 (hepatocellular cancer cell line) cells, known to have methylation rates of 93% and 4.7%, respectively, in the CpG sites of the CDO1 promoter region, were included." (PMID 37740473, 2023). "Promoter DNA of the CDO1 gene was frequently methylated in breast, esophagus, lung, bladder, gastric, and colorectal cancers." (PMID 26785325, 2016). "Using a microarray-based approach, Brait and colleagues identified CDO1 expression to be modulated in colorectal cancer cell lines by promoter methylation and following treatment with the DNA demethylating agent 5-aza-2′-deoxycytidine." (PMID 24351290, 2014). "Our research has focused on the epigenetic silencing of cysteine dioxygenase type 1 (CDO1) in colorectal cancer (CRC)." (PMID 25469504, 2014). "Recent literatures of the significant association between CDO1 methylation and poor prognosis have been reported in breast, esophageal, renal cells carcinoma, HPV associated malignancies, prostate cancer, gallbladder cancer, and colorectal cancer." (PMID 30934021, 2019). "Furthermore, promoter DNA of the CDO1 gene was frequently methylated in esophagus, lung, bladder, gastric, and colorectal cancers." (PMID 29161283, 2017).
endometrial cancer (8 papers, 2019 to 2026). Primary or metastatic malignant neoplasm involving the endometrium (mucous membrane that lines the endometrial cavity). "The diagnostic accuracy of CDO1 alone and CELF4 alone in diagnosing endometrial cancer was 96.7% and 99%, respectively, with a sensitivity of 73.9% and 62.3% and a specificity of 99.3% and 98.8%, respectively." (PMID 41008854, 2025). "In a study evaluating 120 endometrial cytological specimens, hypermethylated CDO1 showed a sensitivity of 86.4% and specificity of 90.8% for endometrial cancer detection." (PMID 41008854, 2025). "EMPap integrated the methylation levels of BHLHE22 and CDO1 measured via qMSP along with age and BMI using a logistic regression model to calculate the endometrial cancer methylation (EM) score for EC identification." (PMID 39487683, 2024). "EMPap incorporated the methylation status of BHLHE22 and CDO1, along with age and body mass index (BMI), into a logistic regression model to calculate the endometrial cancer methylation (EM) score for identifying EC in cervical scrapings." (PMID 39487683, 2024). "The sensitivity and specificity in endometrial cancer detection for BHLHE22/CDO1 were 84.8% and 88.0%, respectively." (PMID 31779688, 2019). "The analysis of the treatment outcomes for endometrial cancer IA stage G1 showed that the methylation level of CDO1 and CDH13 genes may help to predict a positive treatment outcome (complete response) with high accuracy (AUC = 0.96)." (PMID 38732110, 2024). "In other cancer types, SPON1 promotes the metastasis of human osteosarcoma, while methylated BHLHE22/CDO1/CELF4 panel could be used for endometrial cancer screening." (PMID 33860722, 2021). "Both type I and II endometrial carcinomas could be detected using a BHLHE22/CDO1-based methylation profile, suggesting that they may have common epigenomes." (PMID 31779688, 2019). "Our study demonstrated that the methylation assay of two genes, CDO1 and CELF4, is also a good option amongst the many genes that have been reported for endometrial cancer diagnosis." (PMID 41008854, 2025). "The DNA methylation assay of CDO1 and CELF4 (epiHERA®) on cervical scrapings has high accuracy, sensitivity, and specificity in diagnosing endometrial cancer." (PMID 41008854, 2025). "Our study demonstrated that a combined CDO1 and CELF4 DNA methylation (epiHERA®) assay has a high accuracy (97.3%), sensitivity (84.1%), and specificity (98.8%) in diagnosing endometrial cancer." (PMID 41008854, 2025). "This study evaluates the performance of the CDO1 and CELF4 methylation assay of cervical scrapings in diagnosing endometrial cancer." (PMID 41008854, 2025). "Background/Objectives: Our study evaluates the performance of the CDO1 and CELF4 methylation assay of cervical scrapings in diagnosing endometrial cancer." (PMID 41008854, 2025). "Methylation of CDO1 and CELF4 has been utilized in endometrial cancer detection in patients with postmenopausal bleeding or pre-menopausal abnormal uterine bleeding." (PMID 41008854, 2025). "Two hypermethylated candidate genes, namely, cysteine dioxygenase type 1 (CDO1) and CUGBP Elav-like family member 4 (CELF4), have been identified as potential biomarkers for endometrial cancer." (PMID 38107069, 2023). "We tested the effectiveness of the methylation status of four genes (BHLHE22, CDO1, TBX5, and HAND2) in endometrial cancer detection." (PMID 31779688, 2019). "Utilizing cervical scrapings as a potential genetic material, coupled with the use of DNA hypermethylation in specific genes, including CDO1, CELF4, BHLHE22, POU4F3, MAGI2, CADM1, MAL, miR124-2, ZSCAN12, and GYPC, has been investigated for endometrial cancer detection." (PMID 41008854, 2025).
endometrial cancer (continued). "Our study aimed to determine whether cervical scrapings stored in ThipPrep®, used in conjunction with a DNA methylation assay of genes CDO1 and CELF4 (epiHERA®), are effective in diagnosing endometrial cancer." (PMID 41008854, 2025). "Objective of the study: To determine CDO1, PITX2, and CDH13 gene methylation levels in early endometrial cancer and atypical hyperplasia specimens obtained before organ-preserving treatment in the patients with adequate response and with insufficient response to hormonal treatment." (PMID 38732110, 2024). "Thus, we have shown that an assessment of the CDO1 and CDH13 gene methylation levels in endometrial specimens from patients with endometrial cancer (IA stage G1) can predict the treatment outcome." (PMID 38732110, 2024).
hepatocellular carcinoma (7 papers, 2014 to 2024). A malignant tumor that arises from hepatocytes. "Initially, we evaluated the expression of CDO1 in four human hepatoma cell lines and found that HCCLM3 and Hep3B had relatively low CDO1 expression levels similar to DNMT3L." (PMID 38308276, 2024). "Reduced levels of UHRF1 have been shown to regulate the ferroptosis-related gene CDO1 by epigenetic mechanisms, thus up-regulating the level of CDO1 and increasing the sensitivity of hepatocellular carcinoma and cervical cancer cells to ferroptosis." (PMID 37406020, 2023). "In HBV-related HCC, the degree of CDO1 methylation increases with malignant transformation (chronic hepatitis < cirrhosis < hepatocellular carcinoma)." (PMID 29746493, 2018). "To gain further insight into the mechanism of the Cdo1 gene suppression in cirrhotic rats, we employed in vitro analysis on the regulation of the Cdo1 gene expression using the human hepatoma cell line, HepG2." (PMID 24553827, 2014). "To explore whether DNMT3L regulates the malignant cell phenotype of HCC through CDO1, we assessed whether inhibiting CDO1 could reverse the effects of DNMT3L overexpression on the biological behaviors of hepatoma cells." (PMID 38308276, 2024). "Our analysis of The Cancer Genome Atlas (TCGA) human Liver Hepatocellular Carcinoma (LIHC) dataset confirmed that key genes involved in SAA metabolism, including MAT1A, BHMT, CBS, CTH, and CDO1, are suppressed in HCC compared to normal liver." (PMID 32770044, 2020).
prostate carcinoma (6 papers, 2019 to 2026). A carcinoma that arises from epithelial cells of the prostate gland. "Furthermore, inhibition of CDO1 expression in VCaP prostate cancer cells led to increased cell migration and non-adherent growth." (PMID 42265380, 2026).
cervical cancer (4 papers, 2016 to 2025). A primary or metastatic malignant neoplasm involving the cervix. "Among them, ALOX12B and CDO1 were not expressed in both normal cervical and cervical cancer tissues." (PMID 36313765, 2022). "However, no robust data on CDO1 and CELF4 methylation have been reported in cervical cancer." (PMID 41008854, 2025).
gallbladder cancer (4 papers, 2017 to 2019). "Regarding the relationship between methylation abnormalities in CDO1 and expression of CDO1 protein, our previous studies showed a significant relationship in gallbladder cancer." (PMID 29746493, 2018). "Prospective validation is further needed to clarify the relationship between CDO1 promotor DNA methylation and prognosis in primary gallbladder cancer." (PMID 29161283, 2017). "For example, corresponding non-cancerous tissues were relatively highly methylated for CDO1 gene in gallbladder cancer, and threshold cut-off value became high and the frequencies were underestimated." (PMID 30934021, 2019). "In this study, we assessed for the first time the clinicopathological significance of CDO1 methylation in primary gallbladder cancer (GBC) in comparison with non-malignant gallbladder disease." (PMID 29161283, 2017).
glioma (4 papers, 2014 to 2025). A benign or malignant brain and spinal cord tumor that arises from glial cells (astrocytes, oligodendrocytes, ependymal cells). "High CSA levels were correlated with high CDO1 expression in grade 4 glioma compared with grade 2 glioma; both GSH and hypotaurine levels were also higher in glioblastoma." (PMID 41154707, 2025). "The differential expression of CBS, CDO1, and TfR1 underscores a metabolic vulnerability in high-grade gliomas." (PMID 41154707, 2025). "Endogenous hypotaurine derives from two synthetic pathways in which ADO and CDO1 serve as key enzymes; however, but their respective roles in gliomas are unclear." (PMID 33483477, 2021). "Such a cellular status inhibits apoptosis and therefore tumorigenesis is enhanced in glioma cells, where CDO1 or CSA is augmented." (PMID 26785325, 2016). "CDO1 expression was then determined in an independent dataset using immunohistochemical staining on a glioma tumor microarray." (PMID 24351290, 2014). "Of particular interest, we also found that ADO regulates CDO1 expression in glioma cell lines." (PMID 33483477, 2021). "Collectively, these findings suggest that ADO regulates CDO1 expression in glioma." (PMID 33483477, 2021). "The results suggested that ADO, like CDO1, may play an essential role in glioma progression." (PMID 33483477, 2021). "To explore the relevance of ADO expression in glioma progression, we first evaluated the expression of ADO and CDO1, enzymes involved in hypotaurine synthesis, in a panel of glioblastoma cell lines." (PMID 33483477, 2021). "Hitherto, the role of ADO, the enzyme responsible for the t biosynthesis of hypotaurine in a parallel pathway to CDO1/CSA, in glioma tumorigenesis and progression remains undefined." (PMID 33483477, 2021). "In here, we obtained evidence that ADO may function in parallel with the CDO1/CSA axis to drive hypotaurine production and thereby the growth of aggressive high-grade gliomas." (PMID 33483477, 2021). "As cysteine catabolism along this metabolic pathway has not been previously studied in the context of tumor biology, as an initial investigation, we tested the hypothesis that CDO1, which metabolizes CSA from cysteine, would be aberrantly expressed in high-grade glioma." (PMID 24351290, 2014).
non-small cell lung carcinoma (4 papers, 2019 to 2024). A group of at least three distinct histological types of lung cancer, including non-small cell squamous cell carcinoma, adenocarcinoma, and large cell carcinoma. "Another highly down-regulated gene, CDO1 (FC −60.54), encodes cysteine dioxygenase type 1 and is a tumor suppressor found silenced by promoter methylation in different cancer types, such as non-small cell lung cancer and gastrointestinal cancers, including liver cancer." (PMID 34440260, 2021). "Notably, CDO1 is preferentially silenced by promoter methylation in human non-small cell lung cancers (NSCLC) harboring mutations in KEAP1, the negative regulator of NRF2." (PMID 31107239, 2019). "A recent report showed that cysteine sulfinic acid (CSA) and sulfite (SO32-), the byproducts of CDO1-mediated metabolism, were detrimental to the viability in non-small cell lung cancer cells." (PMID 36526626, 2022).